ARF6 (ARF GTPase 6)
Description:
GTP-binding protein involved in protein trafficking that regulates endocytic recycling and cytoskeleton remodeling. GTP-bound form plays an important role in the transport of multiple palmitoylated proteins form the Golgi to the plasma membrane. Required for normal completion of mitotic cytokinesis (By similarity). Plays a role in the reorganization of the actin cytoskeleton and the formation of stress fibers (By similarity). Involved in the regulation of dendritic spine development, contributing to the regulation of dendritic branching and filopodia extension. Potentiates the neurite outgrowth in primary neurons by interacting with the molecular adapter APBB1. Plays an important role in membrane trafficking, during junctional remodeling and epithelial polarization. Regulates surface levels of adherens junction proteins such as CDH1 (By similarity). Required for NTRK1 sorting to the recycling pathway from early endosomes (By similarity). (Microbial infection) Functions as an allosteric activator of the cholera toxin catalytic subunit, an ADP-ribosyltransferase. (Microbial infection) Plays a key role in the endocytosis of enterovirus 71 and thus viral entry into brain microvascular endothelial cells.
Tractability: Small molecule: a structure with a bound ligand is known; a high-quality ligand is known; it has a high-quality binding pocket. Antibody: UniProt places it where antibodies can reach, with high confidence; its Gene Ontology location is reachable by antibodies, with high confidence. PROTAC: ubiquitination databases record sites on it; its protein half-life has been measured; a small molecule that binds it is known.
Gene: Protein-coding gene on chromosome 14 (49,892,608 to 49,897,054, forward strand). Ensembl gene ENSG00000165527.
Subcellular location: Cytoplasm, cytosol; Cell membrane; Endosome membrane; Recycling endosome membrane; Cell projection, filopodium membrane; Cell projection, ruffle; Cleavage furrow; Midbody, Midbody ring; Early endosome membrane; Golgi apparatus, trans-Golgi network membrane
Subcellular location (Human Protein Atlas): Cytosol
Pathways (Reactome):
Vesicle-mediated transport: Clathrin-mediated endocytosis; TBC/RABGAPs
Signal Transduction: MET receptor recycling
Gene Ontology:
Molecular function: G protein activity; GDP binding; GTP binding; GTPase activity; protein binding; protein-macromolecule adaptor activity; thioesterase binding
Biological process: cortical actin cytoskeleton organization; endocytic recycling; positive regulation of actin filament polymerization; positive regulation of mitotic cytokinetic process; positive regulation of neuron projection development; positive regulation of protein secretion; protein localization to cleavage furrow; protein localization to endosome; protein localization to plasma membrane; regulation of filopodium assembly; regulation of Rac protein signal transduction; ruffle assembly; cell adhesion; intracellular protein transport; negative regulation of receptor-mediated endocytosis; positive regulation of focal adhesion disassembly; positive regulation of keratinocyte migration; positive regulation of protein localization to plasma membrane; protein localization to cell surface; regulation of dendritic spine development; vesicle-mediated transport; cellular response to nerve growth factor stimulus; maintenance of postsynaptic density structure; negative regulation of dendrite development; negative regulation of protein localization to cell surface; and 3 more
Cellular component: cell cortex; cleavage furrow; cytosol; endocytic vesicle; endosome; endosome membrane; extracellular exosome; filopodium membrane; Flemming body; focal adhesion; Golgi apparatus; lysosomal membrane; membrane; midbody; plasma membrane; recycling endosome membrane; ruffle; early endosome membrane; cytoplasm; early endosome; glutamatergic synapse; postsynapse; presynapse; recycling endosome
Genetic constraint (gnomAD): Loss-of-function variants: 0 observed, 11.91 expected, observed/expected ratio (o/e) 0, 90% interval 0 to 0.25. The synonymous counts are far from expectation, so gnomAD's model fits this gene poorly and the ratio says little. Missense variants: 75 observed, 249.61 expected, observed/expected ratio (o/e) 0.3, 90% interval 0.25 to 0.36. Synonymous variants: 127 observed, 98.86 expected, observed/expected ratio (o/e) 1.28, 90% interval 1.11 to 1.49.
Homologues: Orthologues: chimpanzee ARF6 (100% identical), dog ARF6 (100% identical), guinea pig ARF6 (100% identical), mouse Arf6 (100% identical), pig ARF6 (100% identical), rabbit ARF6 (100% identical), rat Arf6 (100% identical), tropical clawed frog arf6.2 (99% identical), zebrafish arf6a (99% identical), Drosophila melanogaster Arf6 (97% identical), macaque ARF6 (81% identical). Paralogues in human: ARF1 (70% identical), ARF3 (70% identical), ARF4 (66% identical), ARF5 (66% identical), ARL1 (56% identical), TRIM23 (55% identical), ARL3 (46% identical), ARL4A (45% identical), ARL2 (45% identical), ARL4C (45% identical), ARL5B (43% identical), ARL11 (43% identical), and 18 more.
Diseases named in the same sentence as ARF6 in open-access papers:
ARF6 is named in the same sentence as 124 diseases in open-access papers, as found by Europe PMC text mining. Sharing a sentence is not in itself a finding about the gene and the disease. The quoted sentences say what the papers report.
breast carcinoma (66 papers, 2008 to 2025). "The ARF6 pathway was shown to be overexpressed in triple-negative breast cancer and to be associated with breast cancer invasion and metastasis." (PMID 39530738, 2024). "Breast cancer invasiveness has been linked to ASAP1 activation by ARF6, which is in turn activated by EGFR ligation to GEP10035." (PMID 27910913, 2016). "Taken together, our study demonstrated that Arf6 activation plays a potential role in EGF-induced E-cadherin internalization, providing new mechanism underlying the effect of Arf6 on promoting breast cancer cell metastasis." (PMID 25678857, 2015). "Future studies will be required to decipher the underlying mechanism and function of ARF6-dependent actin waves and their importance for breast cancer cell migration." (PMID 25799492, 2015). "AMAP1 colocalizes with ARF6 at invadopodia, and its knockdown efficiently inhibits invadopodia formation and invasive activities in highly invasive human breast cancer cell lines." (PMID 37834383, 2023). "It is previously indicated that ARF6 is involved in the development of several cancers, such as breast cancer and renal cell carcinomas, lung cancer, head and neck squamous cell carcinoma." (PMID 37716993, 2023). "Our previous studies have shown that breast cancer cells with mesenchymal properties utilize the ARF6 pathway for invasion and metastasis." (PMID 37834383, 2023). "We previously demonstrated that simvastatin, as well as silvestrol, and GGT-II silencing inhibit the invasion of breast cancer cells overexpressing the ARF6-based pathway, and also decrease the cell surface expression of PD-L1 in PDAC cells." (PMID 37834383, 2023). "Studies have found that cancer-derived lEVs are enriched in ADP-ribosylation factor 6 (ARF6) which was shown to trigger the shedding of EVs from breast cancer and prostate cancer cell lines." (PMID 35454972, 2022). "ACAP1 is involved in cell membrane transport and cell migration, is an Arf6 GAP, that is, important for immune cell migration and infiltration, and is associated with tumor immune infiltration and prognosis in breast cancer." (PMID 35432443, 2022). "Increased expression of another ARF6 GEF, EFA6A, has been shown in glioma and linked to promoting invasiveness, while EFA6B (in breast cancer) and EFA6R (in ovarian cancer) have been shown to play possible roles as tumour suppressors." (PMID 35143561, 2022). "Subsequently, we identified GEP100 as a guanine-nucleotide exchange factor that activates Arf6 in the acquisition of invasive and metastatic traits of breast cancer cells upon activation of the epidermal growth factor (EGF)receptor pathway." (PMID 36408139, 2022). "GEP100/BRAG2 (an ARF6 GEF) expression is higher in invasive breast carcinoma, and its recruitment to EGFR in breast cancer cells results in ARF6 activation and stimulation of cell invasion." (PMID 35143561, 2022). "By stimulating invasion ability, disrupting E-cadherin-mediated cell adhesion, and inducing the recycling of β-catenin, the high expression of ARF6 promotes the development of breast cancer, renal cell carcinoma, lung adenocarcinoma and colorectal cancer." (PMID 34991661, 2022). "A downstream role of Arf6 in Wnt signalling would be of particular relevance to pathologies such as colorectal and breast cancers induced by hyperactivation of Wnt signalling." (PMID 34779478, 2021). "Conversely, Arf6 silencing inhibits the invasive capacity of melanoma, glioma and breast cancer cells." (PMID 33673086, 2021). "In this report, we describe CTC in vitro biochemical characterization and show that it blocks both the Arf6-stimulated collective migration and cell invasion in a 3D collagen I gel of the invasive breast cancer cell line MDA-MB-231." (PMID 33673086, 2021). "Various studies analysing invasive breast cancer cell lines have demonstrated that Arf6 is an important player of the migratory and invasive processes." (PMID 33673086, 2021).
breast carcinoma (continued). "Further study exerted that miR-139-5p was expressed at a low level in breast cancer tissues compared with corresponding normal tissues, while ARF6 was expressed at a relatively high level." (PMID 34299149, 2021). "A strong correlation between high levels of Arf6 expression and invasive properties of breast cancer cells has been established." (PMID 33673086, 2021). "Pitavastatin and simvastatin have both been shown to inhibit breast cancer proliferation in vitro and in vivo by inhibiting RhoA, NF-κB, Arf6 or PI3K signaling." (PMID 32541798, 2020). "After BRAG2 binding to phosphorylated EGFR, ARF6 is activated in breast cancer cells, leading to the formation of invadopodia with recruitment of Cortactin, Paxillin and the ARF GAP ASAP1." (PMID 32426352, 2020). "We have shown previously in vitro that combination of conventional anticancer drugs with statins, the MVP inhibitors, is very effective to kill breast cancer cells, if cells overexpress the Arf6-based pathway." (PMID 29329590, 2018). "Overexpression of the Arf6-based pathway in breast cancer cells appears to account for the poor overall survival of the majority of patients who die within several years after their diagnosis." (PMID 29329590, 2018). "The molecules involved in MT1-MMP trafficking and the contribution to breast cancer invasion is possibly due to the ARF6 and kinesin-1/KIF5B." (PMID 29642589, 2018). "The Arf6-based pathway appears to account for the poor overall survival of approximately 50% of breast cancer patients who die within several years after their initial diagnosis." (PMID 29329590, 2018). "Its protein product activates the Arf6 protein, the expression of which has been shown to be higher in highly invasive breast cancer than in weakly invasive or noninvasive breast cancer and normal mammary epithelial cells." (PMID 28362817, 2017). "As expected, we found a positive correlation between elevated levels of ARF6 and breast cancer of higher histological grades." (PMID 26908458, 2016). "Our IHC data for ARF6 are supported by previous studies performed on a breast cancer TMA that showed an increase of ARF6 level in breast tumor metastasis cores and up-regulation, at the plasma membrane, in high-grade triple-negative breast cancers." (PMID 26908458, 2016). "Collectively, the ARF6-based pathway driven by the ZEB1-EPB41L5 axis appears to account for almost half the population of breast cancer patients that survive for less than several years after diagnosis under current therapeutics." (PMID 27617643, 2016). "In conclusion, our study demonstrated that the ZEB1-EPB41L5 axis is at the core of the mesenchymal program of breast cancer, which carries out ARF6-mediated invasion, metastasis and drug resistance." (PMID 27617643, 2016). "ADP-ribosylation factor 6 (ARF6), another critical protein in invasive breast cancer cells, enhances tumor invasion through the regulation of E-cadherin localization and cell-cell adhesion in triple-negative breast cancer." (PMID 27374087, 2016). "Here we show that clear cell renal cell carcinomas (ccRCCs) frequently utilize the Arf6-based mesenchymal pathway to promote invasion and metastasis, similar to breast cancers." (PMID 26854204, 2016). "Our previous results have shown that Arf6 exerts pro-migratory action in breast cancer cells after EGF stimulation." (PMID 25678857, 2015). "ARF6 protein over expression was found to be between 10 and 20-fold higher in highly invasive breast cancer cell lines when compared to non-invasive and normal epithelial cells." (PMID 26185744, 2015). "Taken together, these results demonstrated that Arf6 activation is required for EGF-induced E-cadherin internalization in breast cancer cells." (PMID 25678857, 2015). "Our study provides further evidence for the known activation and plasma membrane localization of Rac1 by ARF6 in breast cancers, suggesting a potential contribution for this pathway during the invasive process." (PMID 25799492, 2015).
breast carcinoma (continued). "Here we show that overexpression of an ARF6 fast-cycling mutant in MDA-MB-231 breast cancer-derived cells to mimick ARF6 hyperactivation observed in invasive breast tumors induced a striking rearrangement of the actin cytoskeleton at the ventral cell surface." (PMID 25799492, 2015). "Arf6 is well characterized in the EGF pathway, which has been associated with breast cancer invasion." (PMID 25779663, 2015). "Recent studies suggest a link between up-regulation of ARF6 expression and activity and the invasive capacity of breast cancer cells." (PMID 25799492, 2015). "Immunoblotting and immunofluorescence assays showed that transfection breast cancer cells with Arf6-T27N or Arf6 siRNA suppressed EGF-induced E-cadherin internalization." (PMID 25678857, 2015). "Despite the fact that EGF signaling stimulates EMT of breast cancer cells, the effect of Arf6 on internalization of E-cadherin of breast cancer cells under EGF treatment remains to be determined." (PMID 25678857, 2015). "We have shown previously that the Arf6 pathway is crucial in promoting the invasion and metastasis of some breast cancer cells." (PMID 24116160, 2013). "IQSEC1 links epidermal growth factor receptor signaling to ARF6 activation to induce breast cancer invasion." (PMID 23202957, 2012). "In fact, the PH domain of GEP100 was identified to bind directly to Tyr1068/1086-phosphorylated EGFR and was required for EGF-stimulated Arf6 activation in MDA-MB-231 breast cancer cells." (PMID 22701712, 2012). "GEP100 links epidermal growth factor receptor signaling to Arf6 activation to induce breast cancer and lung cancer invasion." (PMID 22662237, 2012). "We have shown previously that different breast cancer cells overexpress both Arf6 and its effector, AMAP1; and that overexpressed Arf6 and AMAP1 then constitute a robust signaling axis to induce invasion and metastasis." (PMID 21858086, 2011). "We have shown previously that Arf6 activity greatly contributes to the invasive and metastatic activities of breast cancer cells, when Arf6 is activated by GEP100/BRAG2 and employs AMAP1/DDEF1/ASAP1 as a downstream factor." (PMID 21966491, 2011). "Most malignant breast cancer cells with high invasive activities abnormally overexpress both Arf6 and AMAP1 proteins, while weakly- or non-invasive breast cancer cells express only marginal levels of these two proteins." (PMID 21858086, 2011). "Among them, GEP100 (also called BRAG2) is responsible for Arf6 activation which induces breast cancer cell invasion and metastasis." (PMID 19416474, 2009). "We found that Arf6 and its effector AMAP1 are abnormally overexpressed in malignant breast cancer cells, and this Arf6 signaling pathway is specifically involved in the invasive and metastatic activities of some breast cancer cells." (PMID 19416474, 2009). "HMECs also expressed high levels of Arf6 mRNA, as observed in highly invasive breast cancer cell lines." (PMID 19416474, 2009). "Pathological analyses also revealed that several components of this Arf6 pathway are excellent indicators of the invasive and malignant phenotypes of primary breast cancers." (PMID 19416474, 2009). "We have shown that co-overexpression of GEP100 and Arf6 in MCF7 breast cancer cells induces invasiveness, which is substantially dependent on EGF stimulation." (PMID 19416474, 2009). "Furthermore, the MVP inhibitor statins were found to inhibit TGFβ1-induced ARF6 activation and invasion in breast cancer cells, and also reduced tumor cell resistance to chemotherapeutic agents." (PMID 37834383, 2023). "Thus, the ARF6-based mesenchymal pathway appears to promote tumor malignancy of breast cancer in cooperation with MVP activity." (PMID 37834383, 2023). "ARF6 could enhance the internalization of E-cadherin, disrupting cell-cell adhesion, thereby promoting metastasis and proliferation of breast cancer cells." (PMID 37716993, 2023). "The role of Arf6 in tumor progression is well established in breast cancer models." (PMID 33673086, 2021).